RSPH14 (radial spoke head 14 homolog)
Description:
Functions as part of axonemal radial spoke complexes that play an important part in the motility of sperm and cilia.
Synonyms: RTDR1
Tractability: Small molecule: a structure with a bound ligand is known.
Gene: Protein-coding gene on chromosome 22 (23,059,415 to 23,145,021, reverse strand). Ensembl gene ENSG00000100218.
Subcellular location: Cytoplasm, cytoskeleton, flagellum axoneme
Subcellular location (Human Protein Atlas): Nucleoli
Gene Ontology:
Molecular function: protein binding
Biological process: cilium movement; flagellated sperm motility
Cellular component: 9+2 motile cilium; axoneme; cilium; radial spoke; sperm flagellum
Genetic constraint (gnomAD): Loss-of-function variants: 23 observed, 24.97 expected, observed/expected ratio (o/e) 0.92, 90% interval 0.66 to 1.3. The upper end of that interval is the gene's LOEUF score, 1.3, which puts it in group 5 of 6, group 1 being the genes least tolerant of losing a copy. Missense variants: 424 observed, 434.1 expected, observed/expected ratio (o/e) 0.98, 90% interval 0.9 to 1.06. Synonymous variants: 170 observed, 183.47 expected, observed/expected ratio (o/e) 0.93, 90% interval 0.82 to 1.05.
Homologues: Orthologues: chimpanzee RSPH14 (99% identical), macaque RSPH14 (93% identical), guinea pig RSPH14 (67% identical), pig RSPH14 (66% identical), rabbit RSPH14 (66% identical), dog RSPH14 (64% identical), rat Rsph14 (63% identical), mouse Rsph14 (63% identical), tropical clawed frog rsph14 (47% identical), zebrafish rsph14 (45% identical).
Diseases named in the same sentence as RSPH14 in open-access papers:
RSPH14 is named in the same sentence as 10 diseases in open-access papers, as found by Europe PMC text mining. Sharing a sentence is not in itself a finding about the gene and the disease. The quoted sentences say what the papers report.
hepatocellular carcinoma (2 papers, 2022 to 2023). A malignant tumor that arises from hepatocytes. "High RSPH14 expression appears to be related to poor prognosis of hepatocellular carcinoma (HCC)." (PMID 35305640, 2022). "Despite the high RSPH14 expression in hepatocellular carcinoma, we observed that the relationship between the expression levels of RSPH14 and RFS and OS in HCC patients rendered opposing results to those in the GEPIA database, potentially owing to the relatively small sample size." (PMID 37564197, 2023).
rhabdoid tumor (2 papers, 2021 to 2022). An aggressive malignant embryonal neoplasm usually occurring during childhood. "Recent studies have demonstrated that RSPH14 is associated with human diseases, such as in rhabdoid tumors, duodenal adenocarcinoma, congenital heart disease, meningiomas, and circulating parathyroid hormone formation." (PMID 34351079, 2021). "RSPH14 has been reported to be heterozygously or homozygously lost in pediatric rhabdoid tumors." (PMID 34351079, 2021). "Radial Spoke Head 14 Homolog (RSPH14), also called rhabdoid tumor deletion region gene 1 (RTDR1), is located in a region deleted in pediatric rhabdoid tumor of the brain, kidney, and soft tissues." (PMID 35305640, 2022).
duodenal adenocarcinoma (1 paper, 2021). A carcinoma that arises from glandular epithelial cells of the duodenum. "RSPH14 has been reported to be related to multiple human diseases, including duodenal adenocarcinoma and meningiomas, but the role of RSPH14 in NSCLC remains unclear." (PMID 34351079, 2021).
liver cancer (1 paper, 2022). An epithelial or non-epithelial malignant neoplasm that arises from the liver. "Based on the Human Protein Atlas data, a high expression level of RSPH14 is associated with a poor prognosis of patients with liver cancer." (PMID 35305640, 2022). "A database analysis suggested that high RSPH14 expression is associated with poor prognosis of patients with liver cancer, supporting the present study." (PMID 35305640, 2022).
tumor (3 papers, 2010 to 2023). "The results showed that silencing of RSPH14 partially reversed the enhanced effect of tumor growth induced by knocking down lnc-ZEB2-19." (PMID 37564197, 2023). "RSPH14 knockdown significantly decreased tumor growth and resulted in lower tumor weight and volume (P < 0.001)." (PMID 35305640, 2022). "The expression of RSPH14 was higher in HCC tumor tissues than in adjacent normal tissues and was closely related to unfavorable prognostic factors and poorer survival (all P < 0.05)." (PMID 35305640, 2022). "Notably, the expression level of RSPH14 increased with the increase of tumor differentiation degree, lymph node metastasis, and tumor stage (all P < 0.05)." (PMID 35305640, 2022). "Knockdown of RSPH14 inhibited tumor growth in vivo (P < 0.05)." (PMID 35305640, 2022). "Mechanistically, lnc-ZEB2-19, as a tumor suppressor gene, inhibits the activation of NF-kappa B by interacting with TRA2A to decrease the stabilization of RSPH14 mRNA." (PMID 37564197, 2023). "In order to investigate the expression of RSPH14 in HCC tissues and adjacent normal tissues, we retrieved data from the UALCAN database and found that the expression level of RSPH14 was higher in tumor tissues compared with adjacent normal tissues in HCC patients (P < 0.05)." (PMID 35305640, 2022). "Second, the role of the RSPH14-RelA axis has not been clarified in xenograft tumor models." (PMID 35305640, 2022).
cancer (2 papers, 2021 to 2023). A tumor composed of atypical neoplastic, often pleomorphic cells that invade other tissues. "In addition, the results demonstrated that RSPH14 was involved in regulating cancer apoptosis and cell cycle." (PMID 34351079, 2021). "The biological functions of RSPH14 in human cancers remain largely unknown." (PMID 34351079, 2021). "Next, RNA-Seq was conducted to explore the downstream gene of lnc-ZEB2-19, and RSPH14, a gene recognized as a prognostic marker in HCC20 and NSCLC34 for the promotion of cancer progression, was selected and demonstrated to be a common target of lnc-ZEB2-19 and TRA2A." (PMID 37564197, 2023).
RSPH14 also shares sentences with these, for which no sentence is quoted: colorectal tumours (1 paper); congenital heart disease (1); meningioma (1); non-small cell lung carcinoma (1).